SOD1 (superoxide dismutase 1)
Description:
Destroys radicals which are normally produced within the cells and which are toxic to biological systems. Catalyzes the oxidation of hydrogen sulfide (H2S) to sulfate, playing an important role in detoxifying H2S and limiting the accumulation of reactive sulfur species (RSS) such as persulfides and polysulfides.
Synonyms: hSod1; IPOA; ALS; ALS1; HEL-S-44; SOD; STAHP; homodimer
Tractability: Small molecule: a structure with a bound ligand is known; it has a high-quality binding pocket. Antibody: its Gene Ontology location is reachable by antibodies, with high confidence. PROTAC: UniProt records ubiquitination sites on it; ubiquitination databases record sites on it; its protein half-life has been measured; a small molecule that binds it is known.
Target class: Enzyme
Gene: Protein-coding gene on chromosome 21 (31,659,633 to 31,668,931, forward strand). Ensembl gene ENSG00000142168.
Subcellular location: Cytoplasm; Nucleus
Subcellular location (Human Protein Atlas): Nucleoplasm; Cytosol
Pathways (Reactome):
Cellular responses to stimuli: Detoxification of Reactive Oxygen Species
Hemostasis: Platelet degranulation
Immune System: Gene and protein expression by JAK-STAT signaling after Interleukin-12 stimulation
Gene Ontology:
Molecular function: copper ion binding; identical protein binding; protein binding; protein homodimerization activity; protein phosphatase 2B binding; protein-folding chaperone binding; small GTPase binding; superoxide dismutase activity; zinc ion binding; enzyme binding; metal ion binding
Biological process: heart contraction; hydrogen peroxide biosynthetic process; positive regulation of cytokine production; positive regulation of oxidative stress-induced intrinsic apoptotic signaling pathway; positive regulation of superoxide anion generation; reactive oxygen species metabolic process; regulation of GTPase activity; regulation of mitochondrial membrane potential; removal of superoxide radicals; response to superoxide; superoxide metabolic process; anterograde axonal transport; auditory receptor cell stereocilium organization; embryo implantation; glutathione metabolic process; intracellular iron ion homeostasis; locomotory behavior; muscle cell cellular homeostasis; myeloid cell homeostasis; negative regulation of neuron apoptotic process; neurofilament cytoskeleton organization; ovarian follicle development; peripheral nervous system myelin maintenance; placenta development; positive regulation of apoptotic process; and 29 more
Cellular component: cytoplasm; cytoplasmic vesicle; cytosol; dendrite cytoplasm; extracellular exosome; extracellular region; mitochondrial intermembrane space; mitochondrion; neuronal cell body; nucleoplasm; nucleus; peroxisome; plasma membrane; protein-containing complex; superoxide dismutase copper chaperone complex; mitochondrial matrix; axon cytoplasm; dense core granule; lysosome; secretory granule
Genetic constraint (gnomAD): Loss-of-function variants: 6 observed, 7.69 expected, observed/expected ratio (o/e) 0.78, 90% interval 0.43 to 1.51. That is too few expected variants to judge how well the gene tolerates losing a copy. Missense variants: 106 observed, 146.57 expected, observed/expected ratio (o/e) 0.72, 90% interval 0.62 to 0.85. Synonymous variants: 62 observed, 57.74 expected, observed/expected ratio (o/e) 1.07, 90% interval 0.87 to 1.33.
Gene-disease validity (ClinGen):
ClinGen rates the evidence that SOD1 causes each of these diseases.
amyotrophic lateral sclerosis type 1 (autosomal dominant): Definitive.
Homologues: Orthologues: chimpanzee SOD1 (100% identical), guinea pig SOD1 (86% identical), mouse Sod1 (84% identical), rabbit SOD1 (84% identical), rat Sod1 (83% identical), macaque SOD1 (81% identical), dog SOD1 (81% identical), pig SOD1 (79% identical), zebrafish sod1 (70% identical), tropical clawed frog sod1 (68% identical), Drosophila melanogaster Sod1 (61% identical), Caenorhabditis elegans sod-4 (51% identical). Paralogues in human: CCS (47% identical), SOD3 (40% identical).
Diseases named in the same sentence as SOD1 in open-access papers:
SOD1 is named in the same sentence as 872 diseases in open-access papers, as found by Europe PMC text mining. Sharing a sentence is not in itself a finding about the gene and the disease. The quoted sentences say what the papers report.
amyotrophic lateral sclerosis (1,069 papers, 2005 to 2026). Amyotrophic lateral sclerosis (ALS) is a neurodegenerative disease characterized by progressive muscular paralysis reflecting degeneration of motor neurons in the primary motor cortex, corticospinal tracts, brainstem and spinal cord. "The tracer was designed to be a proxy for tofersen (Qalsody; Biogen), an ASO approved for the treatment of amyotrophic lateral sclerosis in adults who have a variant in the SOD1 gene (SOD1-ALS)." (PMID 41233143, 2026). "Mutations in the antioxidant enzyme superoxide dismutase-1 (SOD1) are a well-established cause of amyotrophic lateral sclerosis (ALS)." (PMID 41664997, 2026). "It was approved by the FDA in 2023 for the treatment of amyotrophic lateral sclerosis (ALS) associated with mutations in the SOD1 gene." (PMID 40874255, 2025). "Tofersen was approved in 2023 for the treatment of amyotrophic lateral sclerosis, specifically in patients diagnosed with mutations in the superoxide dismutase 1 (SOD1) gene." (PMID 41465141, 2025). "Two hundred eight genetic mutations in SOD1 have been linked to amyotrophic lateral sclerosis (ALS)." (PMID 40859014, 2025). "On 25 April 2023, the FDA granted approval for tofersen to treat amyotrophic lateral sclerosis (ALS) associated with mutations in the superoxide dismutase 1 (SOD1) gene." (PMID 40430531, 2025). "In amyotrophic lateral sclerosis, the accumulation of copper and zinc ions leads to mutations and the aggregation of superoxide dismutase 1, which damages motor neurons." (PMID 40724240, 2025). "Tofersen, an antisense oligonucleotide, has recently received FDA and EMA approval for treating amyotrophic lateral sclerosis (ALS) in adults with SOD1 gene mutations." (PMID 39820998, 2025). "Tofersen (QALSODY®) is an antisense oligonucleotide co-developed by Ionis Pharmaceuticals and Biogen that was approved by the FDA in 2023 to treat amyotrophic lateral sclerosis (ALS) associated with a superoxide dismutase-1 (SOD1) gene mutation." (PMID 41091236, 2025). "SOD1 is fundamental for antioxidant defense in the cytosol and mutations in SOD1 have been implicated in neurodegenerative disorders such as amyotrophic lateral sclerosis (ALS)." (PMID 41008976, 2025). "Tofersen (Qalsody) is a 20-mer ASO gapmer with mixed PS/PO linkages, approved to treat amyotrophic lateral sclerosis (ALS) with superoxide dismutase 1 (SOD1) mutation in 2023 (U.S. Food and Drug Administration, 2023b)." (PMID 41394159, 2025). "The association between deficient copper and SOD1 mutations has also been observed in amyotrophic lateral sclerosis (ALS)." (PMID 40957494, 2025). "In 2023, Tofersen was approved in the United States for the treatment of adult amyotrophic lateral sclerosis with mutations in the superoxide dismutase 1 (SOD1) gene." (PMID 41311831, 2025). "Overexpression of SIRT1 even extended the lifespan of mice with amyotrophic lateral sclerosis (ALS) associated with SOD1 mutation." (PMID 41502422, 2025). "Tofersen is the first effective and approved therapy for superoxide dismutase 1 (SOD1)‐associated amyotrophic lateral sclerosis (ALS [SOD1‐ALS])." (PMID 40781905, 2025). "Protein misfolding and aggregation in superoxide dismutase 1 (SOD1) are linked to the neurodegenerative disease amyotrophic lateral sclerosis (ALS)." (PMID 40475252, 2025). "Missense mutations in SOD1 are identified as the second most common cause of amyotrophic lateral sclerosis (ALS; Ref." (PMID 39172219, 2025). "Disease‐modifying treatments targeting the core pathological process for SOD1‐linked amyotrophic lateral sclerosis (ALS) are becoming available." (PMID 40548824, 2025).
amyotrophic lateral sclerosis (continued). "Cu/Zn superoxide dismutase 1 (SOD1) mutations serve as a model for elucidating the destabilizing effects on protein folding and misfolding linked to the lethal neurological disease, amyotrophic lateral sclerosis (ALS)." (PMID 40070688, 2025). "High-copy superoxide dismutase 1 glycine 93 to alanine (SOD1-G93A) transgenic mice exhibit mutations associated with amyotrophic lateral sclerosis (ALS)." (PMID 39940644, 2025). "We profiled changes in ion channel expression in amyotrophic lateral sclerosis patient–derived motor neurons carrying a superoxide dismutase 1(A4V) mutation to identify what drives their hyperexcitability." (PMID 38911266, 2024). "Misfolding of superoxide dismutase-1 (SOD1) is a pathological hallmark of amyotrophic lateral sclerosis (ALS) with SOD1 mutations." (PMID 38891791, 2024). "Since the antisense oligonucleotide tofersen has recently become available for the treatment of amyotrophic lateral sclerosis (ALS) caused by mutations in SOD1, determining the causality of the over 230 SOD1 variants has become even more important." (PMID 39054363, 2024). "In contrast, the specific inhibitor G6PDi−1 prevented neuronal death caused by the expression of mutated SOD1 or TDP43 proteins in a model of amyotrophic lateral sclerosis, indicating a beneficial effect of G6PDH activity on cells in pathological conditions." (PMID 38339211, 2024). "Qalsody is prescribed for the management of amyotrophic lateral sclerosis (ALS) in adults with a mutation in the superoxide dismutase 1 (SOD1) gene." (PMID 38399458, 2024). "A structural alteration in copper/zinc superoxide dismutase (SOD1) is one of the common features caused by amyotrophic lateral sclerosis (ALS)–linked mutations." (PMID 39126203, 2024). "Based on these results, the FDA approved tofersen in April 2023 for the treatment of patients with amyotrophic lateral sclerosis associated with a mutation in the SOD1 gene, followed by the EMA’s Committee for Human Medicines (CHMP) approval in February 2024." (PMID 38732027, 2024). "Mutations in SOD1 have been linked to amyotrophic lateral sclerosis (ALS), a progressive neurodegenerative disease." (PMID 39743988, 2024). "Because of the association between abnormal excitability and accelerated disease progression in amyotrophic lateral sclerosis, we set out to find its molecular basis in MNs with the SOD1(A4V) mutation." (PMID 38911266, 2024). "For instance, among genetic mutations linked to known hNDDs, examples include HTT gene mutation in HD, SOD1 in amyotrophic lateral sclerosis, PSEN1, PSEN2, and APP in AD, ARSA gene mutation in metachromatic leukodystrophy (MLD), and others." (PMID 39200370, 2024). "Research yields credible data supporting the implication of oxidants originating from mitochondria and mitochondrial oxidative injury in amyotrophic lateral sclerosis-associated mutant Cu/Zn superoxide dismutase (SOD1)." (PMID 38474354, 2024). "Tofersen was approved in April 2023 for the treatment of amyotrophic lateral sclerosis (ALS) associated with mutations in the SOD1 gene." (PMID 37662844, 2023). "SOD1 had been associated with Amyotrophic lateral sclerosis (ALS) and was recently linked to Alzheimer’s disease." (PMID 37004691, 2023). "SOD1 has been implicated in animal models to play a mechanistic role in various human health conditions including amyotrophic lateral sclerosis (ALS), cardiac ischemia, and even AKI." (PMID 37821813, 2023). "An essential role of SOD1 has been implicated across various disease states, including amyotrophic lateral sclerosis (ALS), motor neuropathy, cancer, and inflammatory diseases." (PMID 37243148, 2023). "Mutations in the gene coding for Sod1 are linked to amyotrophic lateral sclerosis (ALS), probably through the effect of mutations on the cellular proteostatic balance." (PMID 36978953, 2023).
amyotrophic lateral sclerosis (continued). "Beginning with the identification of SOD1 as a genetic cause of amyotrophic lateral sclerosis (ALS), C. elegans have contributed to a deeper understanding of the mechanistic underpinnings of this devastating neurodegenerative disease." (PMID 38239833, 2023). "Mutations in SOD1 gene account for 20% of amyotrophic lateral sclerosis cases, and promote activation of caspases, cytoskeletal abnormalities, and mitochondrial dysfunction." (PMID 37259454, 2023). "SOD1 was the first gene associated with both familial and sporadic forms of amyotrophic lateral sclerosis (ALS) and is the second most mutated gene in Caucasian ALS patients." (PMID 37265463, 2023). "Familial forms of amyotrophic lateral sclerosis with mutations in the gene superoxide dismutase 1 (SOD1) are now treated with Tofersen, an intrathecally administered antisense oligonucleotide against SOD1, showing encouraging results in patients." (PMID 36746939, 2023). "Mutations in the gene superoxide dismutase 1 (SOD1) are causative for familial forms of the neurodegenerative disease amyotrophic lateral sclerosis." (PMID 36715870, 2023). "We chose G93A and A4V mutations in the Sod1 gene to model amyotrophic lateral sclerosis (ALS) disease-related mutations." (PMID 37353834, 2023). "Mutations in SOD1 can cause amyotrophic lateral sclerosis, probably via a toxic gain-of-function involving protein aggregation and prion-like mechanisms." (PMID 36793789, 2023). "Clusters of increased microglial activation have further been reported in temporal and occipital regions in asymptomatic and symptomatic SOD1 gene mutated amyotrophic lateral sclerosis carriers." (PMID 37751068, 2023). "SOD1 is a homodimeric cytoplasmic and nuclear protein involved in neutralizing free radicals, and mutations in SOD1 are associated with amyotrophic lateral sclerosis (ALS) type I." (PMID 37153596, 2023). "Genetic mutations in TARDBP, C9orf72, MAPT and SOD1 have been used to classify frontotemporal dementia and amyotrophic lateral sclerosis." (PMID 35202463, 2022). "Superoxide dismutase 1 (SOD1) is one of the causative genes associated with amyotrophic lateral sclerosis (ALS), a neurodegenerative disorder." (PMID 35053410, 2022). "This example can be understood through the familial Amyotrophic Lateral Sclerosis (ALS) caused by mutations in the Superoxide Dismutase 1 (SOD1) gene." (PMID 35976325, 2022). "Amyotrophic lateral sclerosis is an autosomal dominant disease, and some cases are associated with a defective protein, superoxide dismutase 1 (SOD1), whose accumulation leads to a loss of motor neurons in the spinal cord and brain." (PMID 36032737, 2022). "Lastly, the mutant form of superoxide dismutase 1 (SOD1), linked to amyotrophic lateral sclerosis (ALS), has been shown to be secreted via a nutrient starvation-induced UPS pathway in yeast and HeLa cells." (PMID 35774225, 2022). "Mutations in superoxide dismutase 1 gene (SOD1) are linked to amyotrophic lateral sclerosis (ALS), a neurodegenerative disorder predominantly affecting upper and lower motor neurons." (PMID 34996976, 2022). "Cu/Zn superoxide dismutase 1 (SOD1) has a high propensity to misfold and form abnormal aggregates when it is subjected to oxidative stress or carries mutations associated with amyotrophic lateral sclerosis." (PMID 36592929, 2022). "SOD1 is important for all organisms; in eukaryotes, its deletion causes a reduction in human lifespan, and mutations in H. sapiens are linked with amyotrophic lateral sclerosis." (PMID 36363706, 2022). "This is of clinical interest given that one of the most common genetic forms of amyotrophic lateral sclerosis (ALS) is due to polymorphisms in the human SOD1 gene, with mouse models recapitulating these findings." (PMID 35280283, 2022). "Genetically polymorphic Superoxide Dismutase 1 G93A (SOD1-G93A) underlies one form of familial Amyotrophic Lateral Sclerosis (ALS)." (PMID 35280283, 2022).
amyotrophic lateral sclerosis (continued). "Copper-zinc superoxide dismutase (SOD1) has been proposed as one of the causative proteins of amyotrophic lateral sclerosis (ALS)." (PMID 35817830, 2022). "SOD1 dysregulation has been associated with many diseases, including amyotrophic lateral sclerosis (ALS), cancer, accelerated aging, and age-related diseases." (PMID 35204309, 2022). "In the amyotrophic lateral sclerosis case studies, examining penetrance for variants in the SOD1 and C9orf72 genes, we make novel penetrance estimates which correspond closely to understanding of the disease." (PMID 36522764, 2022). "For example, many SOD1 mutations can cause amyotrophic lateral sclerosis (ALS), NF1 mutations can cause pediatric brain tumors, RB1 mutations can cause retinoblastoma, and ETV6 mutations can cause pediatric acute lymphoblastic leukemia." (PMID 36276986, 2022). "The deficiency or wrong combination of metal ions in Cu, Zn-superoxide dismutase (SOD1), is regarded as one of the main factors causing the aggregation of SOD1 and then inducing amyotrophic lateral sclerosis (ALS)." (PMID 36364128, 2022). "Here, we establish an approach for monitoring the redox state of live motor neurons with SOD1 mutations associated with amyotrophic lateral sclerosis." (PMID 35624228, 2022). "Among the different enzymes involved in the antioxidant response, SOD1 and DJ-1 have both been associated with the pathogenesis of amyotrophic lateral sclerosis and Parkinson’s disease, suggesting a possible interplay in their mechanism of action." (PMID 36009245, 2022). "Over 160 mutations have been identified throughout the gene encoding copper/zinc (Cu/Zn) superoxide dismutase 1 (SOD1) that are known to cause the motor neuron disease amyotrophic lateral sclerosis (ALS)." (PMID 35065969, 2022). "The key molecular mechanisms linked to motor neuron vulnerability in amyotrophic lateral sclerosis have been extensively studied using transcriptional profiling in motor neurons isolated from adult mutant superoxide dismutase 1 mice." (PMID 35445192, 2022). "Dominant mutations in the gene encoding Cu/Zn superoxide dismutase 1 (SOD1) account for 20–25% of the inherited forms of amyotrophic lateral sclerosis (ALS)." (PMID 36555655, 2022). "As a model for studying ROS accumulation, SOD1 knockout mice have been proven to cause continuous and extensive oxidative damage, exhibiting liver cancer, amyotrophic lateral sclerosis, bone loss, and increased bone fragility." (PMID 36299607, 2022). "It has been well established that mutations of the SOD1 gene are implicated in the etiology of amyotrophic lateral sclerosis (ALS), one of the NDs." (PMID 33921907, 2021). "In the SOD1 mouse model of amyotrophic lateral sclerosis, it was already shown that a sporadic loss of transgene copy number can occasionally occur, probably by internal recombinations." (PMID 34050505, 2021). "In good agreement with our results, oral memantine treatment did not result in improved rotarod performance in the Ts65Dn mouse model of Down syndrome or the G93A SOD1 mutation model of amyotrophic lateral sclerosis." (PMID 32914393, 2021). "The importance of SOD1 in motor neuron degeneration is also confirmed by the demonstrated association between SOD1 defects in skeletal muscle and amyotrophic lateral sclerosis (ALS)." (PMID 33805942, 2021). "In the murine model SOD1-G93A that mimics amyotrophic lateral sclerosis (ALS), which causes skeletal muscle fibrosis, the treatment with AM095, an LPA1 inhibitor, causes motor skills improvement evaluated by grip strength, rotarod, and runtime." (PMID 33689121, 2021). "Mutant SOD1 variants cause familial forms of amyotrophic lateral sclerosis and α-synuclein is the main constituent of Lewy bodies which are a prominent pathological hallmark of PD." (PMID 32322926, 2021). "Mutations in SOD1 are also associated to familial cases of Amyotrophic Lateral Sclerosis (ALS), a devastating neurodegenerative disorder." (PMID 33439432, 2021).